KLF4 (KLF transcription factor 4)
Diseases named in the same sentence as KLF4 in open-access papers (continued):
Sharing a sentence is not in itself a finding about the gene and the disease.
cancer (continued). "The association between colorectal anti-cancer gene KLF4 and metastasis is inhibited by reduced METLL14, which promotes KLF4 mRNA degradation in a IGF2BP2-dependent manner in CRC." (PMID 37965577, 2023). "To further test the stemness of NSCLC/PTX-resistant cells, we examined the expression of stemness-associated markers, including KLF4, OCT4, and c-MYC, hallmarks of cancer stem cells." (PMID 38068934, 2023). "In cancer, KLF4 has been demonstrated to be either oncogenic or anti-oncogenic depending on the cancer type, and therefore performs unique functions in different CSCs." (PMID 37614497, 2023). "In general, the dual effect of KLF4 on cancers depend on the type/subtype of cancer and the molecular regulation in signaling pathways." (PMID 37031197, 2023). "Precisely, KLF4 interplays with the transcription factor Sox9, and both antagonize β-catenin and inhibit TCF activity in cancer cells, rendering KLF4 as another candidate therapeutic target against cancer." (PMID 37047552, 2023). "ADM can further develop into PanIN and progresses to PanIN-3 as carcinoma in situ, and consistently, KLF4 gradually increases in PanIN." (PMID 37031197, 2023). "Among the H3K27me3-marked genes activated by CTX treatment, Egr4 and Klf4 were both transcription factors extensively studied in cancers." (PMID 37963880, 2023). "In some tumors, analysis in combination with important downstream molecules of KLF4 will yield more information assisting cancer diagnosis and prognosis." (PMID 37031197, 2023). "Recent studies have demonstrated increased KLF4 levels in cancer stem cell (CSC) spheroids generated from CRC cell lines." (PMID 37173904, 2023). "KLF4 can restrain the migration and proliferation of cancer cells by inhibiting downstream molecules of WNT signaling, such as cyclinD1 and c-Myc, and directly regulating the WNT/β-catenin pathway to inhibit EMT." (PMID 36761967, 2023). "ADSL silencing significantly upregulated the mRNA and protein expression levels of cancer stem cell–related transcription factors, namely, Oct-4, Nanog, KLF4, and SOX4, as indicated by qRT-PCR and Western blotting." (PMID 37976135, 2023). "This IL-6 expression was found to be regulated by Kruppel-like factor 4 (KLF4) through histone acetylation, as KLF4 levels were found to be downregulated in various types of cancer." (PMID 36672677, 2023). "To determine if ERβ and its variants have any effect on the stemness of the cancer cells, we analyzed expression of Yamanaka factors OCT4, SOX2, and KLF4 that induce pluripotency in normal cells." (PMID 36982940, 2023). "KLF4 has been known to activate the mesenchymal program in cancer stem cells through the increased activity of the TGFB1/SMAD signaling." (PMID 38129585, 2023). "While KLF4 has been extensively studied in cancer, the potential clinical application of KLF4 for cancer diagnosis and prognosis has not been adequately studied, and it is still a still far from clinical transition." (PMID 36936440, 2023). "We searched the relevant literature that evaluated the prognostic value of KLF4 in different cancers, and the original survival data were obtained from the text, tables or Kaplan–Meier curves for both comparative groups." (PMID 35177016, 2022). "Simvastatin administration significantly reduced KLF4 expression and prevented the adriamycin-induced enhancement of metastasis and cancer stemness in OS cells." (PMID 36499521, 2022). "In the stratified analyses according to cancer type, high KLF4 expression indicated better prognosis in patients with GC, HCC, PDAC and CRC, with a pooled HR of 0.59 (95% CI: 0.53–0.65, P < 0.001) for OS." (PMID 35177016, 2022). "KLF family of zinc finger transcription factors KLF4 activates the p38 signaling pathway in osteosarcoma, promoting cancer stemness." (PMID 35501462, 2022).
cancer (continued). "A second mechanism involves the control of TERT gene expression by the Kruppel-like transcription factor 4 (KLF4), which maintains hTERT levels in human embryonic stem cells and cancer cells." (PMID 35348914, 2022). "A precedent for such negative regulation of FOXM1 by KLF4 can be found in gastric and pancreatic cancer." (PMID 35852857, 2022). "Mechanistically, E2F3-induced MEX3A overexpression sustains cancer cells in a rapidly dividing and undifferentiated state by directly suppressing KLF4, a key pro-differentiation regulator, to activate WNT signaling." (PMID 36276637, 2022). "In patient histological tissue samples the epithelial markers as Cytokeratin, E-cadherin and KLF4 got decreased towards to the border of the cancer cell nests." (PMID 35219646, 2022). "Mean optical intensities of E-cadherin and KLF4 continuously decreased from the middle of the cancer cell nest towards the border, whereas slug intensities slightly increased in the same direction." (PMID 35219646, 2022). "In this study, we conducted a systematic review and meta-analysis to summarize the global findings in using KLF4 for the prediction of the clinical results of cancer patients." (PMID 35177016, 2022). "MYC is a gene frequently involved in cancer, and it is one of the four genes (in addition to Oct4, Sox2, and Klf4) that can reprogram fibroblasts to become pluripotent stem cells." (PMID 34991589, 2022). "KLF4 is a transcription factor that has an important role in cell differentiation, proliferation, and survival, especially in the context of cancer." (PMID 35757505, 2022). "The stemness-associated markers OCT4, NANOG, SOX2, KLF4 and c-MYC are expressed in numerous cancer types suggesting the presence of cancer stem cells (CSCs)." (PMID 34685477, 2021). "This iron chelator inhibited the expression of Nanog, c-Myc, SOX2, OCT3/4, and KLF-4 in four cancer cell lines (HSC-2: Oral squamous cancer, TE-4, and OE33: Esophageal cancer, and NT-2: Embryonal cell carcinoma)." (PMID 35008527, 2021). "That correlation turned out to be correct and supported by studies showing the role of KLF4 in promoting and maintaining cancer stem cells." (PMID 35008527, 2021). "Cell cycle arrest and chemotherapy resistance are other features of cancer stem cells, and we detected changes in the cell cycle after knocking out Sox2 or Klf4 under hypoxia." (PMID 33762574, 2021). "By contrast, KLF4 enhances the stemness of osteosarcoma cells by activating p38 signaling, conferring metastatic potential to cancer cells." (PMID 33435156, 2021). "KLF4 is a transcription factor which appears to function as an oncogene and a tumor suppressor gene in different cancer types." (PMID 34685477, 2021). "The first important finding of this paper is that we confirmed the result of other researchers that KLF4 gene expression was significantly decreased in human cancer tissues compared with normal mucosa controls." (PMID 33802627, 2021). "A recent study revealed different elements of the ubiquitination process that are involved in the regulation of KLF4 protein stability in various cell types and cancers." (PMID 34114341, 2021). "To develop a deeper understanding of KLF4′s role in the metabolism of cancer cells, we aimed to characterize how KLF4 responds to metabolic stressors, and the molecular pathways underlying these responses." (PMID 33917010, 2021). "KLF4 expression was found to be lower in cancers with a more mesenchymal phenotype, as measured by their higher KS-based EMT scores." (PMID 34680284, 2021). "These ATF3-induced tumors were also found to have reduced expression of Mir145 and Mir143, leading to upregulation of the transcription factors Klf4 and Sox2 and the cancer stem cell-related gene Kras, respectively." (PMID 33652981, 2021).
cancer (continued). "Since many cancer cell lines are known to suppress KLF4 expression, we investigated the metabolic differences that arise from altering the level of KLF4 in MEFs and RKO cells." (PMID 33917010, 2021). "Given the tendency of cancer cells to downregulate KLF4, we hope that our findings contribute to understanding cancer metabolism despite using only one cancer cell line." (PMID 33917010, 2021). "Meanwhile, PC-9/GR/sh-BTK cells exhibited significantly lower levels of cancer stemness markers such as KLF4, SOX2, NANOG, and CD133, than its counterparts, whereas the pBTK-N1 cells expressed the highest levels of these markers." (PMID 34315851, 2021). "In clinical studies, KLF4 is frequently found to be either overexpressed or underexpressed in cancer cells, both of which are correlated with poor prognosis." (PMID 33917010, 2021). "The discordant data about KLF-4 and Oct3/4 expression can be due to the fact that, besides controlling cancer cell reprogramming, they also regulate the epithelial-to-mesenchymal transition, modulating phenomena such as migration and proliferation." (PMID 34055629, 2021). "It is worth noting that LR004-VC-MMAE also downregulated cancer stemness-related genes, such as Oct4, Sox2, KLF4 and EpCAM." (PMID 34879870, 2021). "miR-7 also inhibited the stemness of prostate stem cancer cells through repression of KLF4 and PI3K/Akt/p21 downstream pathway." (PMID 33806891, 2021). "KLF4 is a transcriptional factor whose role in carcinogenesis is context-dependent, being upregulated or downregulated in different types of cancer." (PMID 35008527, 2021). "LR004-VC-MMAE also inhibited the activation of EGFR signaling and the expression of cancer stemness marker genes such as Oct4, Sox2, KLF4 and EpCAM." (PMID 34879870, 2021). "Curcumin is extensively applied with CP in suppressing progression of cancer cells and providing their chemosensitivity via targeting molecular pathways and mechanisms such as apoptosis, metastasis, KLF4 and SOX2." (PMID 33921908, 2021). "The overexpression of microRNA-92a (MiR-92a) in CRC facilitates CRC growth and invasion through the targeting of kruppel-like factor 4(KLF4) and downstream p21, and a reduction in miR-92a can cause apoptosis of cancer cells." (PMID 33618627, 2021). "We observed a reduced methylation of KLF4 in many cancers with reduced KS scores, such as HNSC, ESCA, and COAD." (PMID 34680284, 2021). "The expression of HeyL, together with the stemness-associated genes SOX2, OCT4, KLF4, and CD44, was significantly increased in PCSCs compared with the corresponding bulk cancer cells." (PMID 35096586, 2021). "In CP resistant-cancer cells, KLF4 and ROS undergo down-regulation that are responsible for increased cell viability." (PMID 33921908, 2021). "Together, these datasets across cancer types reveal a robust reduction in KLF4 expression with the onset of EMT." (PMID 34680284, 2021). "This connection between cell death and glucose starvation would likely make dysregulation of KLF4 especially problematic in cancer cells." (PMID 33917010, 2021). "In normal tissue, KLF4 is detectable in the nuclei of terminally differentiated epithelial cells, whereas, its expression is frequently lost in various human cancer types, such as colorectal cancer, gastric cancer, esophageal squamous cell carcinoma." (PMID 33802627, 2021). "Stemness-related factors OCT4, SOX2, NANOG, and KLF4 are common transcriptional regulators in cancer stem cells." (PMID 33436575, 2021). "To substantiate these in vitro observations with clinical data, we compared KLF4 levels across cancers in The Cancer Genome Atlas (TCGA)." (PMID 34680284, 2021). "In line with this, Klf4 expression has been correlated with inhibition of c-Jun N-terminal kinase (Jnk) which reportedly triggers EMT during cancer metastasis." (PMID 34195082, 2021).
cancer (continued). "KLF4′s effect on cancer has been found to be context dependent due to differential regulation between cell types as well as its ability to act as both a transcriptional activator and a repressor." (PMID 33917010, 2021). "Here, we reported that abridged miR-135a expression in OS cells and tissues, and its expression is inversely correlated with the expression of BMI1 and KLF4, which are described as oncogenes in several cancers." (PMID 33828977, 2021). "KLF4 is a target gene of miR-107, receiving increasing attentions on its role in promoting cancer cell metastasis." (PMID 32674073, 2020). "KLF4 favors cancer cell survival and escape from treatment, depending on cancer type and patient population." (PMID 33231937, 2020). "It has been reported that the transcription factor complex of POU5F1, SOX2, and KLF4 binds to the Nanog promoter to induce cellular reprogramming and cancer stemness." (PMID 32978904, 2020). "We found that DMU-214 caused a significant increase in mRNA expression of IGFBP3 and KLF4, which have been reported to inhibit cancer cell migration as well as proliferation." (PMID 32046103, 2020). "A previous study also demonstrated that KLF4 activated the p38 MAPK signaling pathway to promote cancer stemness." (PMID 33052880, 2020). "Krüppel-like factor 4 (KLF4) is a transcription factor that was firstly identified as a regulator of cell growth arrest being one of the most important factors in Cancer Stem Cells (CSC)." (PMID 32410997, 2020). "Cancer stem cells that are highly metastatic to the brain express lower miRNA-7, modulating the stem-like capacity of cancer cells through KLF4 expression in breast cancer cell lines and nude mice." (PMID 31900168, 2020). "Recently, a role of KLF4 was reported in inducing pluripotent stem cells and also maintaining the stemness of cancer stem cells." (PMID 32156068, 2020). "There is a direct relationship between the expression of OCT4B1 and stemness-related genes (OCT4, SOX2, NANOG, and KLF4), and its downregulation in cancer cell lines inhibits the expression of these genes[24 ▶]." (PMID 32429647, 2020). "Although there are conflicting studies about the role of KLF4 in HCC tumorigenesis, KLF4 is repeatedly reported by recent studies as a regulator of CSCs in various cancers." (PMID 32408542, 2020). "Subsequently, the downregulation of miR-145 leads to higher expression of cancer stemness regulatory genes Krüppel-like factor 4 (KLF4) and high-mobility group AT-hook 2 (HMGA2) and thus chemoresistance." (PMID 32756406, 2020). "Even though there are studies claiming that Klf4 inhibits β-catenin, there are other reports showing that the Klf4 / β-catenin complex is necessary for the self-renewal capacity of stem/cancer cells." (PMID 32429174, 2020). "Here, we report the novel finding that (ADP‐ribosyl)ation (PARylation) of KLF4 by Poly [ADP‐ribose] polymerase 1 (PARP1) regulates KLF4 chromatin recruitment following DNA damage response, which provides potential novel strategies for targeted cancer therapy." (PMID 33231937, 2020). "These discoveries shed new light on the functioning, regulation and significance of KLF4 in various types of cancer." (PMID 33266506, 2020). "Stemness markers promote cancer stem cell-like formation, such as SOX2, Nanog, Oct-4, CD44, c-Myc, and KLF4, are linked to drug resistance." (PMID 33082357, 2020). "In cancer, KLF4 function is frequently lost due to hypermethylation of CpG islands in the promotor region." (PMID 32756406, 2020). "Krüppel-like factor 4 (KLF4) is a member of the KLF family of transcription factors that mediate growth inhibition in several types of human cancers, including AML2–4." (PMID 33219287, 2020). "In light of the fact that two of the factors used in the original reprogramming cocktail (c-Myc and Klf4) had established roles in carcinogenesis, it is crucial to understand the degree to which the roles of these proteins overlap in pluripotency and cancer." (PMID 32298395, 2020).
cancer (continued). "A study performed in cancer stem cell (CSC)-enriched spheroid CRC cell lines revealed a role of KLF4 in the invasiveness, migration, resistance to treatment, and ability to generate tumors as well as in the induction CSCs markers in those cells." (PMID 32410997, 2020). "Cancer stem cells play pivotal role in malignant cells transformation.Reprogramming genes, such as Nanog, KLF4, EpCAM, c-Myc, Sox2 andp-Oct4 induce the origin of CSCs." (PMID 32779438, 2020). "In HCT116RR, derived radio-resistant cancer cells, KLF4 directly interacts with the human telomeric RAP1 protein." (PMID 33266506, 2020). "In the present review we focus on the role of KLF4 in the most common types of cancer, as the vast majority of recent reports are concerned with these cancer types." (PMID 33266506, 2020). "In various cancer cell lines, exogenous KLF4 expression is known to suppress cell motility and invasion by decreasing the mesenchymal gene expression while upregulating the epithelial gene expression." (PMID 32408542, 2020). "Among them, six transcription factors regulating the cancer stem cell-associated genes were verified by the reported literatures (marked with deep red), including NR4A1, FOS, KLF-4, GLI1, NFATC1 and JUN." (PMID 32242101, 2020). "Although the most recent review of its key roles in development, cellular reprogramming and cancer appeared in 2017, since then many new reports have explored the roles played by KLF4 in cancer." (PMID 33266506, 2020). "In this study, we used murine induced pluripotent stem cells that expressed specific stem cell genes such as Nanog, Oct3/4, Sox2, Klf4, and c-Myc, and two human cancer cell lines with similar stem cell gene expression." (PMID 30717462, 2019). "The primary cultured cells derived from the malignant tumors and metastatic nodules sustained the expression of stemness markers, such as Nanog, Klf4 and c-Myc, and acquired cancer stem markers, such as CD90, CD44 and ALDH1." (PMID 31450740, 2019). "Because different types of cancer show dysregulated cell growth, KLF4 has been considered a key factor in cancer development and progression." (PMID 31040909, 2019). "The KLF4 decreases in cancers such as colon and esophagus, the brain, kidneys, prostate, bladder, and leukemia in advanced stage of the disease." (PMID 31724937, 2019). "A meta-analysis based on the database ONCOMINE found that KLF4 transcript levels are lower in this type of cancer." (PMID 31040909, 2019). "Our current study verified that KLF4, a critical transcriptional factor that had been reported to be involved in the development of different cancers, was the upstream target of PODXL." (PMID 29748877, 2019). "Previous studies reported that CSC biomarkers such as NANOG, OCT4, SOX2, KLF4 and ALDH1A1 were associated with a poor prognosis in several cancers." (PMID 29615105, 2018). "KLF4 is a dual-function transcription factor, which can exert its role as an oncogene or a tumor suppressor gene depending on the cancer type or cancer stage." (PMID 30297986, 2018). "Collectively, we propose a new role for KLF4 in cancer-induced pre-metastatic niche formation and provide new insight into the formation of pre-metastatic niche." (PMID 30568162, 2018). "Altogether, these findings unveil a previously unexplored role of PHGDH in the regulation of self-renewal and stemness factors (KLF4, Oct4, Nanog, Sox-2, and Lin28B) in cancer stem-like cells." (PMID 30250195, 2018). "For instance, several stemness markers, such as OCT4, C-MYC, KLF4, NANOG, SALL4, and SOX2 are reported to be highly expressed in various cancers and associated with poor clinical outcomes of patients." (PMID 29747452, 2018). "The commonly reported specific surface markers, such as CD44, CD133, OCT-4, Bmi-1, ALDH1, ABCG2 and KLF4, with high expressions, are usually used to isolate cancer stem cells from cell lines." (PMID 29559853, 2018).